SATB2 (SATB homeobox 2)
Diseases named in the same sentence as SATB2 in open-access papers (continued):
Sharing a sentence is not in itself a finding about the gene and the disease.
serous carcinoma (2 papers, 2022 to 2025). "In addition to morules, we showed that SATB2 expression by tumor cells is extremely rare in endometrial cancer; thus, SATB2 can be reliably used in the diagnostic evaluation of a uterine endometroid or serous carcinoma, if necessary." (PMID 41321186, 2025). "In conclusion, we showed that SATB2 expression is extremely rare in a large series of primary endometrial endometroid and serous carcinomas as well as in a small series of endocervical adenocarcinomas." (PMID 41321186, 2025). "SATB2 expression can be reliably used in the differential diagnosis of primary endometrial endometrioid and serous carcinomas as well as primary endocervical adenocarcinomas because nearly all of these tumors are SATB2‐negative." (PMID 41321186, 2025).
small bowel adenocarcinomas (2 papers, 2020 to 2025). "Special AT-rich sequence-binding protein 2 (SATB2) is a transcription factor expressed by colonic cryptic epithelium and epithelial neoplasms of the lower gastrointestinal (GI) tract, as well as by small bowel adenocarcinomas (SBAs), though at a lower rate." (PMID 33228145, 2020). "Unlike SATB2, cytokeratin patterns stratified small bowel adenocarcinoma patient prognosis." (PMID 33228145, 2020).
small bowel cancer (2 papers, 2020 to 2024). "We also found SATB2-positive dysplastic components in three cases; however, two of them were SATB2-negative in their invasive component, indicating a marginal role of SATB2 expression in small bowel cancer development." (PMID 33228145, 2020). "Immunostaining was negative for CK7, positive for CK20 and SATB2, and negative for ER and PAX2; therefore, the patient was diagnosed with a uterine metastasis of small bowel cancer." (PMID 39156866, 2024). "Immunostaining was negative for Cytokeratin 7 (CK7), positive for Cytokeratin 20 (CK20) and Special AT-Rich Sequence-Binding Protein 2 (SATB2), and negative for estrogen receptor (ER) and Paired Box Gene 2 (PAX2), leading to a diagnosis of metastatic recurrence of small bowel cancer." (PMID 39156866, 2024).
small intestinal cancer (2 papers, 2020 to 2024). "Taking these evidences into consideration, it is difficult to completely distinguish between colon and small intestinal cancers solely by the expression statuses of CDX2 and/or SATB2." (PMID 32867793, 2020). "Histopathology and immunohistochemistry of the uterine tumor revealed that it was a metastasis of small intestinal cancer (Cytokeratin 7 [CK7] [−], Cytokeratin 20 [CK20] [+], Special AT-Rich Sequence-Binding Protein 2 [SATB2] [+], Paired Box Gene 2 [PAX2] [−], and estrogen receptor [ER] [−])." (PMID 39156866, 2024).
Stroke (2 papers, 2022 to 2023). Sudden impairment of blood flow to a part of the brain due to occlusion or rupture of an artery to the brain. "This allowed to correlate the expression of BCL11B or SATB2 to the structural and functional outcomes, indicating their potential involvement into post-stroke events." (PMID 37237015, 2023). "BCL11B and SATB2 appear as potential molecular markers for predicting better outcomes of the stroke recovery as well as potential targets for therapeutical interventions after ischemic stroke." (PMID 37237015, 2023). "Interestingly, the percentage of neurons (CTIP2+ plus SATB2+) expressing Fos was modestly higher in grafts at the stroke sites than in control sites, which could reflect greater neuronal integration and activity." (PMID 35626693, 2022). "We could not test direct involvement of both BCL11B and SATB2 in the recovery after stroke, as respective mutant mice do not survive after birth and show a plethora of defects, including brain malformations." (PMID 37237015, 2023).
uterine fibroids (2 papers, 2022). "SATB homeobox 2 and neuregulin 1 were proved to be the upregulated hypermethylated genes involved in the pathogenesis of uterine leiomyoma by activating the WNT/β-catenin and TGF-β pathways." (PMID 36386836, 2022). "In SATB2, 88.9% (8 of 9 samples) of the MED12m-positive uterine fibroids and 75% (9 of 12 samples) of the MED12m-negative uterine fibroids showed higher DNA methylation levels (more than 15% DNA methylation) than the myometrium, respectively." (PMID 35618793, 2022). "To know whether mutations in MED12 are associated with the upregulation of upstream regulators, SATB2 and NRG1 in uterine fibroids, we examined the DNA methylation and expression levels of SATB2 and NRG1 in the uterine fibroids with and without MED12 mutations." (PMID 35618793, 2022).
uterine sarcomas (2 papers, 2023 to 2025). "Polo-like kinase 4 (PLK4), Secreted Protein, Acidic and Rich in Cysteine (SPARC) Related Modular Calcium Binding 2 (SMOC2), Special AT-rich Sequence-Binding protein 2 (SATB2), or Forkhead box P3 (FOXP3) + T cells have all been suggested as prognostic indicators for uterine sarcomas." (PMID 37173887, 2023).
ZIKV infection (2 papers, 2017 to 2023). "In our model of ZIKV infection, we observed a massive cell death after 10 dpi that accounts for the loss of SATB2+ neurons and reduction in the corpus callosum." (PMID 38140578, 2023). "ZIKV infection also causes a density reduction in PH3+ cells, intermediate progenitor cells, and SATB2+ neurons." (PMID 38140578, 2023).
adenomyoma (1 paper, 2025). A benign neoplasm characterized by the presence of a glandular and a mesenchymal (fibromyomatous) component. "In our large cohort, we confirmed that there is no stromal SATB2 expression; thus, this expression can be used to distinguish an atypical polypoid adenomyoma from an endometrial carcinoma." (PMID 41321186, 2025).
AIDS (1 paper, 2015). A syndrome resulting from the acquired deficiency of cellular immunity caused by the human immunodeficiency virus (HIV). "Consistent with our previous results, we found that the relative expression levels of both IGFBP6 and SATB2 were low in all groups of HIV/AIDS patients compared with normal groups." (PMID 26039376, 2015). "After normalization by the β-actin, the expression level of IGFBP6 was down-regulated by 65.9% in HIV/AIDS patients relative to normal controls (P = 0.04, one sided Mann-Whitney U test) while SATB2 was down-regulated by 57.1% (P = 0.027)." (PMID 26039376, 2015). "We found that IGFBP6 and SATB2 were significantly down-regulated in HIV-infected CEM*174 cells and 3 different cohorts of HIV/AIDS patients while their promoters were predominantly hyper-methylated compared with normal controls." (PMID 26039376, 2015).
anal adenocarcinoma (1 paper, 2025). "Positive CK20, CDX2, villin, and SATB2 confirmed adenocarcinoma with intestinal differentiation, while PAX8 negativity ruled out ovarian malignancy, concluding that the lymphadenopathy was likely due to metastasis of anal adenocarcinoma." (PMID 41573493, 2025).
appendiceal adenocarcinoma (1 paper, 2019). "The appendiceal adenocarcinoma also showed positive immunoreaction for CK7, CK20, CDX-2, and SATB2 but was negative for estrogen receptor, progesterone receptor, Pax-8, CD56, synaptophysin, and chromogranin A." (PMID 31409389, 2019). "Both the appendiceal adenocarcinoma and malignant components of the OMT stained positive for CK7, CK20, CDX-2, and SATB2 but negative for estrogen receptor, progesterone receptor, and pax-8." (PMID 31409389, 2019).
apraxia (1 paper, 2021). Apraxia is a neurological disorder characterized by the inability to perform tasks or movements, despite having the desire and physical ability to perform them. "For SATB2‐associated disorder, a previous study reported a diagnosis of childhood apraxia of speech in all 40 individuals with enough verbal ability in their SAS cohort." (PMID 34241948, 2021).
brain ischemia (1 paper, 2023). Diminished or absent blood supply to the brain caused by obstruction (thrombosis or embolism) of an artery resulting in neurologic damage. "This complementarity of their function was also reflected in the BCL11B and SATB2 distribution after brain ischemia." (PMID 37237015, 2023). "Immunohistochemistry revealed a spatial pattern of BCL11B and SATB2 expression after brain ischemia and the results were quantified by measuring integrated optical density of the labelled cells." (PMID 37237015, 2023). "Taken together, an increase of BCL11B and SATB2 after ischemia was accompanied with their positive correlations with the functional recovery and negative correlations with ischemic damage, suggesting their beneficial role in brain ischemia." (PMID 37237015, 2023). "BCL11B increase was observed over both brain hemispheres, however SATB2 increase after brain ischemia was predominant in the contralateral hemisphere that was not directly affected by ischemic damage." (PMID 37237015, 2023).
carcinoid tumor (1 paper, 2025). A slow growing neuroendocrine tumor, composed of uniform, round, or polygonal cells having monotonous, centrally located nuclei and small nucleoli, infrequent mitoses, and no necrosis. "SATB2 expression has also been described in other malignancies, including renal and urologic carcinomas, carcinoid tumors, and small intestinal neoplasms." (PMID 41463263, 2025).
chondrosarcoma (1 paper, 2021). A malignant cartilaginous matrix-producing mesenchymal neoplasm arising from the bone and soft tissue. "Immunohistochemistry showed that vimentin was expressed in 25 cases of dedifferentiated chondrosarcoma, with positive chondrosarcoma S-100 component and positive dedifferentiated chondrosarcoma SATB2." (PMID 33588810, 2021).
clear cell carcinomas (1 paper, 2025). "They identified one usual‐type endocervical adenocarcinoma (0.7%), one endocervical clear cell carcinoma (14.3%), and one endocervical endometroid adenocarcinoma (33.3%) expressing SATB2." (PMID 41321186, 2025).
clear cell sarcoma of the kidney (1 paper, 2025). "BCOR-ITD and YWHAE-rearranged tumors define an infantile SRCS subset with truncal/abdominopelvic predilection, aggressive behavior, and characteristic immunophenotypes (BCOR, cyclin D1, SATB2), overlapping morphologically with clear cell sarcoma of the kidney." (PMID 41514642, 2025).
Cushing syndrome (1 paper, 2023). Cushing's syndrome (CS) encompasses a group of hormonal disorders caused by prolonged and high exposure levels to glucocorticoids that can be of either endogenous (adrenal cortex production) or exogenous (iatrogenic) origin. "Biologically and structurally distinct from these RenNETs are the ACTH-positive RenNETs associated with an ectopic Cushing syndrome and displaying a typical solid-eosinophilic morphology in the absence of ISL1 or SATB2 expression." (PMID 37405461, 2023). "SATB2 was diffusely positive in all non-functioning tumors and negative in Cushing syndrome cases." (PMID 37405461, 2023). "Similarly, SATB2 that labels the lower gastrointestinal epithelium, and the NETs of the rectum (81%) and middle ear NETs (100%), was only found in non-functioning RenNETs and not in Cushing syndrome-related RenNETs." (PMID 37405461, 2023).
dental anomaly (1 paper, 2021). "However, how SATB2 mutation results in human dental anomaly, and its impact to the function of hDPSCs and the underlying mechanism is rarely reported." (PMID 34863303, 2021).
developmental and epileptic encephalopathy (1 paper, 2024). An epilepsy associated with developmental impairment that may be due to either the underlying etiology or the superimposed epileptic activity, or both. "Within the cohort of patients experiencing developmental and epileptic encephalopathy (DEE), WES has revealed genetic variants in novel genes (FGF12, GABBR1, GABBR2, ITPA, KAT6A, PTPN23, RHOBTB2, SATB2) and candidate epilepsy-associated genes (CAMTA1, FAT3, GABRA6, HUWE1, PTCHD1)." (PMID 39523358, 2024).
ductal carcinomas (1 paper, 2009). "SATB2 was associated with ER positivity (ER(-) vs. ER(+) p = 0.0283) within ductal carcinomas." (PMID 19642980, 2009).
dyslexia (1 paper, 2024). A learning disorder characterized by an impairment in processing written words. "We found that several of the individual genetic loci that dispose most significantly to dyslexia were associated with the volumes of primary auditory cortices (Heschl’s gyri), including PPP2R3A, BCL11B, SATB2, and SH2B3." (PMID 39693421, 2024).
endocervical adenocarcinoma (1 paper, 2025). An adenocarcinoma that arises from the endocervix. "Our results confirm that SATB2 expression in usual‐type endocervical adenocarcinoma is rare and focal; thus, it can be reliably used to exclude a colorectal origin." (PMID 41321186, 2025). "used 297 endocervical adenocarcinomas to develop tissue microarrays and perform a broad immunohistochemical panel, including SATB2 with the same EP281 clone." (PMID 41321186, 2025). "One case (3.8%) of endocervical adenocarcinoma focally expressed SATB2." (PMID 41321186, 2025). "Our study detected one usual‐type endocervical adenocarcinoma (3.8%) focally expressing SATB2." (PMID 41321186, 2025). "SATB2 was not expressed in any of the metastatic pancreatic, gallbladder, gastric, or endocervical adenocarcinomas." (PMID 41321186, 2025).
endocervical carcinoma (1 paper, 2025). A carcinoma that arises from epithelial cells of the endocervix. "Whole‐tumor sections of 376 endometrial and 27 endocervical carcinomas were examined for SATB2 expression." (PMID 41321186, 2025).
endometrial carcinoma (1 paper, 2025). A malignant tumor arising from the epithelium that lines the cavity of the uterine body. "Among endometrial carcinomas, we found 10 cases (2.7%) expressing SATB2, all of which were endometrioid adenocarcinomas." (PMID 41321186, 2025). "SATB2 positivity in endometrial carcinomas is almost always restricted to morules within endometrioid adenocarcinomas." (PMID 41321186, 2025). "Only two cases expressed SATB2 in the glandular component, indicating 0.53% positivity in the endometrial cancer group." (PMID 41321186, 2025).
endometrial tumor (1 paper, 2016). "For example, the down-regulation of miR-31 in CAFs and the corresponding increased expression of the homeobox gene SATB2 contributed to the migration and invasiveness of endometrial tumor cells." (PMID 27793031, 2016).
endometrioid adenocarcinoma (1 paper, 2025). An adenocarcinoma characterized by the presence of malignant glandular epithelial cells resembling endometrial cells. "We found 10 cases (2.7%) expressing SATB2, all of which were endometrioid adenocarcinomas." (PMID 41321186, 2025).
esophageal squamous cell carcinoma (1 paper, 2025). Esophageal squamous cell carcinoma (ESCC) is a type of esophageal carcinoma (EC) that can affect any part of the esophagus, but is usually located in the upper or middle third. "A radioresistant esophageal squamous cell carcinoma cell line (KYSE150R) was established using the gradient dose method, and RT-qPCR was used to detect the expression of SATB2 in KYSE150 and KYSE150R cells." (PMID 40078194, 2025).
fibrosarcoma (1 paper, 2023). A malignant mesenchymal fibroblastic neoplasm affecting the soft tissue and bone. "Low-grade fibrosarcoma reveals MDM2, CDK4, and SATB2 positivity." (PMID 37602060, 2023).
fibrous dysplasia (1 paper, 2021). A genetic, non-inheritable disorder caused by osteoblastic differentiation defects that result in the replacement of bone marrow and trabecular bone by fibrous stroma and immature bone. "All cases of benign fibro-osseous lesions of the jaw (ossifying fibroma (n = 7) and fibrous dysplasia (n = 5)) also demonstrated nuclear immunoreactivity with a strong intensity and diffuse staining pattern to SATB2 in the stromal plump and spindle cells." (PMID 35049602, 2021).
gastric tumor (1 paper, 2025). "Immunohistochemically, the gastric tumor cells were positive for CK7, showed very focal CK20, with focal and weak SATB2, and diffuse CDX2 expression, consistent with primary gastric adenocarcinoma." (PMID 41159019, 2025).
gynecological cancers (1 paper, 2024). "SATB2 was infrequently positive in gynecological cancers (12%; 2/17) and kidney cancers (10%; 4/42), while GPA33-positivity was rare." (PMID 37349623, 2024).
head and neck cancer (1 paper, 2023). A primary or metastatic malignant neoplasm affecting the head and neck. "In head and neck cancer, SATB2 could bind with ΔNp63a to inhibit downstream Tap73β transcription which enhanced chemotherapy resistance of cancer cells." (PMID 37107669, 2023).
hemimegalencephaly (1 paper, 2016). "However, abnormal Satb2 expression in the superficial region of the neocortex has been previously reported in FCD type II, showing a different pattern compared to hemimegalencephaly, which is characterized by a diffused Satb2 cortical expression pattern." (PMID 27042238, 2016).
hyperplastic polyp (1 paper, 2023). A polyp found mainly in the stomach and colon. "GS‐II‐HRP staining and SATB2 expression in tubular adenoma, microvesicular hyperplastic polyp, and sessile serrated lesion." (PMID 37036163, 2023).
influenza (1 paper, 2025). An acute viral infection of the respiratory tract, occurring in isolated cases, in epidemics, or in pandemics; it is caused by serologically different strains of viruses (influenzaviruses) designated A, B, and C, has a 3-day incubation period, and usually lasts for 3 to 10 days. "Interestingly, influenza vaccination in early pregnancy has been shown to prevent a reduction in embryonic SATB2 in a rodent model of LPS-induced MIA." (PMID 38961232, 2025).
invasive carcinoma (1 paper, 2025). A carcinoma that is not confined to the epithelium, and has spread to the surrounding stroma. "Three of 25 (12%) CD-SBNs (1 conventional type invasive carcinoma and 2 conventional type dysplasias; 1 dysplasia was adjacent to SATB2 positive invasive carcinoma) were SATB2 positive and all SATB2-positive CD-SBNs showed CDH17 expression, whereas no CLDN18 expression was identified." (PMID 39164422, 2025).
ischemia (1 paper, 2023). A hypoperfusion of the BLOOD through an organ or tissue caused by a PATHOLOGIC CONSTRICTION or obstruction of its BLOOD VESSELS, or an absence of BLOOD CIRCULATION. "Likewise, the increase of BCL11B and SATB2 co-expression after ischemia correlated with the lesion reduction and neurological recovery rates suggesting their combined effect on functional recovery." (PMID 37237015, 2023). "Furthermore, BCL11B and SATB2 expression positively correlated with neurological recovery rate suggesting their beneficial role in damage repair after ischemia." (PMID 37237015, 2023). "Similarly, since the expressions of both BCL11B and SATB2 were increased in the contralateral hemisphere after ischemia, this is also where we identified the highest frequency of their co-expression." (PMID 37237015, 2023).
lung squamous cell carcinoma (1 paper, 2022). "Among them, one circRNA was previously reported to be closely related to cancer: hsa_circ_0051488 sponges miR-6717–5p, thereby regulating the expression of SATB2, which plays a vital role in lung squamous cell carcinoma." (PMID 35309118, 2022).
malignant pleural mesothelioma (1 paper, 2026). A malignant neoplasm that arises from mesothelial cells in the pleura and shows a diffuse growth pattern. "SATB2 expression was high in human malignant pleural mesothelioma (MPM) cell lines but absent in Met5A mesothelial cells." (PMID 41677646, 2026).
medullary colonic carcinoma (1 paper, 2022). "They revealed positive SATB2 expression in 89% of cases making it a promising marker for the detection of medullary colonic carcinoma." (PMID 36819801, 2022).
mesothelioma (1 paper, 2026). A usually malignant and aggressive neoplasm of the mesothelium which is often associated with exposure to asbestos. "This study assessed whether SATB2 overexpression is sufficient to promote in vitro transformation of human mesothelial cells and whether SATB2 suppression in mesothelioma cancer stem cell (CSC)-enriched populations is associated with altered chemoresistance." (PMID 41677646, 2026).